PARP1 (poly(ADP-ribose) polymerase 1)
Diseases named in the same sentence as PARP1 in open-access papers (continued):
Sharing a sentence is not in itself a finding about the gene and the disease.
colon carcinoma (continued). "To ascertain whether Sam68 deletion reduces colon tumor formation as a result of the defect in PARP1 activation and PARylation, we assessed the impact of the PARP inhibitor, Olaparib, on phosphor-p65 and Bcl-XL levels and colon tumor development in Apcmin716/+ mice." (PMID 27458801, 2016). "Rhythmic therapy targeting poly ADP-ribose polymerase-1 (PARP-1) modulates MDSC inhibition and enhances anti-PD-1 immunotherapy in colon cancer." (PMID 39100676, 2024). "Transgelin binds poly ADP-ribose polymerase 1 (PARP1) and regulates the downstream Rho signaling pathway in the metastasis of colon cancer." (PMID 37363722, 2023). "Colon tumor induction upon AOM/DSS challenge was potentiated in MGMT and PARP-1 double knockout mice, demonstrating the important roles of these proteins in the protection against NOC-induced genomic instability and cancer." (PMID 36902118, 2023). "In comparison to the wild type and SIAE knockout cells, our results showed significantly low levels of 25kDa cleaved/inactive PARP1 fragments in the CASD1 knockout lung and colon cancer cells when challenged with mitoxantrone." (PMID 37377914, 2023). "In colon cancer cells, SHP2 was indicated to dephosphorylate poly (ADP-ribose) polymerase 1 (PARP-1) and thus to suppress DNA repair while promoting the cGAS-STING activation to elevate the sensitization of chemotherapy in colon cancer cells." (PMID 37781354, 2023). "In a previous study, ERCC1, PARP1, and AQP1 were identified as poor prognostic biomarkers for colon cancer at stages II-III." (PMID 37234985, 2023). "Besides, death of colon cancer cells could be significantly rescued by blocking PARP1 activity." (PMID 35715817, 2022). "Instead of targeting the three major proteins, PARP-1, a downstream active effector of RIPK1/RIPK3, can be activated by TRAIL and induce necroptosis in colon cancer cells." (PMID 35884370, 2022). "The recurrence of colon cancer can be predicted by 26 autophagy-related genes (ARGs), in which BAX and PARP1 play the most significant role." (PMID 35884370, 2022). "The interaction between PARP1 and transgelin in human RKO colon cancer cells was further validated by immunoprecipitation and immunofluorescence assays." (PMID 32774160, 2020). "Similar cellular response to nutrient deprivation was observed in HCT116 colon carcinoma cells with no apparent apoptotic cleavage of CASPASE-3 or PARP1." (PMID 34848715, 2021). "Furthermore, we observed that and Bcl-xL levels increased, whereas Bcl-xS and cleaved PARP1 levels decreased, in SRPK1-overexpressing colon cancer cells, and the opposite effect was observed in SRPK1 knockdown cell lines." (PMID 34193174, 2021). "Moreover, in colon cancer in vitro and in vivo, ART induced apoptosis by concomitantly increasing the expression of PARP-1 and Bax and decreasing Bcl-2." (PMID 33316936, 2020). "PARP1 and PARP2 were both activated in MSI subtype colon cancer patients’ tissue and cell lines." (PMID 31221124, 2019). "This suggests reciprocal influence of PARP-1 and OGG1 on their expression and stability, and may contribute to progression of colon cancer." (PMID 25526641, 2014). "Our results support a hypothesis that transgelin interacts with PARP1 and regulates the expression of downstream key genes (CALM1, MYO1F, NCKIPSD, PLK4, RAC1, WAS and WIPF1), which are mainly involved in the Rho signaling pathway in the human RKO colon cancer cells." (PMID 32774160, 2020).
colorectal cancer (62 papers, 2014 to 2025). A primary or metastatic malignant neoplasm that affects the colon or rectum. "More recently, PARP-1 has been revealed as a possible target in colorectal cancer, which is the second leading cause of cancer-related death worldwide." (PMID 39456536, 2024). "Studies have proved that PARP1 (Ala762Val, rs1136410) was associated with the susceptibility to colorectal carcinoma of adult and children." (PMID 38907095, 2024). "In colorectal cancer, higher PARP1 expression/activity levels have been associated with CSCs and with advanced/metastatic stages of colorectal cancer disease." (PMID 35326523, 2022). "Few studies have also shown positive association of PARP1 SNPs (rs180404 and rs180414 at position 81 and 284) with Alzheimer’s disease, glioblastoma and protectively associated with colorectal cancer." (PMID 30183716, 2018). "In the present study, we have evaluated the association 3′UTR region SNP of PARP-1 gene (rs8679) with colorectal cancer in 183 cases and 190 age and gender matched controls of Saudi population." (PMID 27746584, 2016). "Our results provide the first evidence that the PARP-1 rs8679 polymorphism was associated with a decreased risk of colorectal cancer in a Saudi population." (PMID 27746584, 2016). "In the present study we observed a significant protective association of PARP-1 rs8679 genotypes in colorectal cancer patients." (PMID 27746584, 2016). "SNP rs8679 of PARP-1 gene showed a statistically significant protective association with Saudi colorectal cancer patients." (PMID 27746584, 2016). "ANP32B may alter the sensitivity of colorectal cancer cells to PARP1 inhibitor via a mechanism associated with the HPF1 gene." (PMID 38192816, 2024). "PARP1 inhibition along with superoxide dismutase 1 (SOD1) inhibition could promote the synthetic lethal killing of RAD54B-deficient colorectal cancer cells." (PMID 32711558, 2020). "Another study also found that PARP1 was highly expressed in 68.2% of colorectal cancer tissues and closely associated with tumor location, indicating that high PARP1 expression may be an important molecular event in colorectal cancer." (PMID 35264225, 2022). "Secondly, it should be verified again in other different colorectal cancer cell lines both in vitro experiments and in vivo experiments to further demonstrate the ability of high expression of PARP1 levels play a vital role in CRC." (PMID 38907095, 2024). "Overexpression of ANP32B also reduced the sensitivity of colorectal cancer cells to PARP1 inhibitor, consistent with the oncogenic role of ANP32B." (PMID 38192816, 2024). "In a colitis-associated colorectal cancer model, AOM was associated with greater tumor number in wild-type mice than in PARP-1−/− mice." (PMID 37730576, 2023). "PARP-1 has been shown to play a role in the development of colorectal cancer, as PARP-1 expression is significantly higher in colorectal cancer than in healthy tissue and directly correlates with tumor size and histopathology." (PMID 37730576, 2023). "PARP-1 suppresses the induction of colorectal cancer, but promotes the progression of colorectal cancer." (PMID 36077221, 2022). "In this experiment, we used cytokeratin 20 (CK20) as a biomarker of colorectal cancer cells, as well as antibodies against cleaved caspase-3 or cleaved PARP-1." (PMID 35267627, 2022). "In this review, we provide an overview of mechanisms, preclinical studies and advances in clinical trials of DNA-PKcs, ATM/ATR, CHK1/CHK2, WEE1 and PARP1 kinase inhibitors combined with radiotherapy for colorectal cancer treatment." (PMID 36230796, 2022). "The removal of the autoinhibitory MAR moieties from PARP-1 by MacroD2 has been suggested to explain the accumulation of MARylated PARP-1 in the context of MacroD2 gene deletion in human colorectal cancer cells." (PMID 30862789, 2019). "In the present study, relative PARP-1 expression is statistically significantly high in colorectal cancer tissue when compared to normal tissue." (PMID 27746584, 2016).
colorectal cancer (continued). "In the present study we are intended to investigate the contribution of PARP-1 3′UTR SNP rs8679 (T3823C) genetic polymorphism and expression level in colorectal cancer among Saudi population." (PMID 27746584, 2016). "The present study has also investigated PARP-1 expression levels in colorectal cancer tissues versus those of matched healthy tissues of the same patient." (PMID 27746584, 2016). "In summary, our data show that patients with colorectal cancer present expression changes in several BER genes, suggesting a role for APE1, XRCC1, PARP1 and OGG1 and APE1 polymorphism in colorectal carcinogenesis." (PMID 25268610, 2014). "In view of the role of the polymorphism in BER enzymes in colorectal carcinogenesis, we evaluated the influence of the APE1 Asp148Glu polymorphism on APE1, XRCC1, PARP1 and OGG1 expression in normal and tumor samples from patients with colorectal cancer." (PMID 25268610, 2014). "Reducing PARP-1 protein levels may effectively prevent induced colorectal cancer by suppressing the expression of cyclin D and STAT3." (PMID 39620145, 2024). "PARP-1 is TCF-4/β-A novel co activator of gene transactivation induced by catenin may play a role in the development of colorectal cancer." (PMID 38907095, 2024). "Moreover, partnership of MARVELD1 and PARP1 promotes resistance to DNA damaging therapy in colorectal cancer (CRC)." (PMID 36750717, 2023). "Our computational study highlighted that MortaparibMild could inhibit PARP1 similar to Olaparib and suggested it to be a good drug candidate against colorectal cancer." (PMID 36172283, 2022). "Our findings support that the upregulation of PARP-1 is associated with tumor progression and poor prognosis in Saudi patients with colorectal cancer, suggesting that PARP-1 can be novel and valuable signatures for predicting the clinical outcome of patients with colorectal cancer." (PMID 27746584, 2016). "Our observations of increased expression of PARP-1 in poor prognosis tumors do lend support to the view that PARP inhibitors might play a role in therapy for colorectal cancer patients." (PMID 27746584, 2016). "Our findings proved that the upregulation of PARP-1 is associated with tumor progression and poor prognosis in Saudi patients with colorectal cancer, suggesting that PARP-1 can be novel and valuable signatures for predicting the clinical outcome of patients with colorectal cancer." (PMID 27746584, 2016). "Univariate analyses were used to assess whether the PARP-1 expression level and various clinicopathological conditions were independent prognostic parameters of colorectal cancer patient outcomes." (PMID 27746584, 2016). "Thus, taking into account the role of BER in colorectal carcinogenesis, the effects of the APE1 Asp148Glu polymorphism on APE1, XRCC1, PARP1 and OGG1 gene expression were evaluated in patients with colorectal cancer." (PMID 25268610, 2014). "Thus, we evaluated the influence of APE1 T2197G (Asp148Glu) polymorphism on APE1, XRCC1, PARP1 and OGG1 expression in normal and tumor samples from patients with colorectal cancer." (PMID 25268610, 2014). "Additionally, the absence of PARP-1 in mice resulted in a notable decrease in the occurrence of colorectal cancer caused by oxymethane (AOM) and dextran sulfate sodium (DSS)." (PMID 39620145, 2024). "Therefore, we focus on the significance of PARP1 in colorectal cancer." (PMID 38907095, 2024). "Considering the synthetic lethality of PARP-1 inhibitors against BRCA-deficient cells, it can be seen that the inhibition ratio of these two compounds is significantly higher in HCT-116 than RKO in the colorectal carcinoma cell lines, which is also consistent with the results of Niraparib." (PMID 36353483, 2022). "In colorectal cancer, PARP1 interacts with MARVELD1 to form a positive feedback loop → stabilizes PARP1 and ↑NAA50‐mediated acetylation → enhances genomic stability and chemoresistance." (PMID 40904702, 2025).
colorectal cancer (continued). "As an apoptosis indicator, CHR plus TMZ treatment also increased cleavage of PARP1 (which plays a critical role in DNA repair), aligning with previous findings that CHR inhibits PARP in colorectal cancer and hepatocellular carcinoma." (PMID 40963691, 2025). "In conclusion, we found that PARP1 was upregulated in CRC and promotes colorectal cancer cells proliferation." (PMID 38907095, 2024). "NCAPD2 is similarly upregulated in colorectal cancer and NCAPD2 inhibits autophagy and promotes CRC cell proliferation and migration through the Ca2+/CAMKK/AMPK/mTORC1 pathway and PARP-1/SIRT1 axis." (PMID 37498296, 2023). "NCAPD2 plays a role in colorectal cancer through Ca2+/CAMKK/AMPK/mTORC1 pathway and PARP-1/SIRT1 axis and can be used as a potential therapeutic target." (PMID 37192046, 2023). "Here, we show that the RSR is efficient in primary CSCs from colorectal cancer (CRC-SCs), and describe unique roles for PARP1 and MRE11/RAD51." (PMID 33531658, 2021). "This prompted us to study the role of PARP-1 in CLytA-DAAO-induced cell death in pancreatic and colorectal carcinoma cell lines." (PMID 33198289, 2020). "This strategy turned out to be successful given that we were able to validate endogenous interactions of P2-HNF4α with PARP1, RAD50 and DNA-PKcs in colorectal cancer cell lines." (PMID 31060309, 2019). "Several of these proteins including PARP1, RAD50, and DNA-PKcs were confirmed to interact with HNF4α in colorectal cancer cell lines." (PMID 31060309, 2019). "RNA sequencing analysis of differentially expressed genes in ANP32B silenced colorectal cancer cells showed that histone PARylation factor 1 (HPF1), which protects against DNA damage by interacting with the anti-tumor target PARP1, was significantly downregulated." (PMID 38192816, 2024). "Moreover, acetylation enhances the interaction of PARP1 with MARVELD1, promoting genomic stability in colorectal cancer cells post-DNA damage." (PMID 39528473, 2024). "A prior study revealed that mRNA expression of APE1 and PARP1 is upregulated in tumor tissue compared with that in non-malignant tissues from 53 paired colorectal cancer patients." (PMID 32111912, 2020). "Specifically, PARP-1 may play an important role in carcinogenesis of colorectal cancer and recent findings have raised the possibility of using PARP inhibitor therapy in colorectal cancers clinical trials." (PMID 24954394, 2014). "Furthermore, our data show that patients with colorectal cancer present expression changes in several BER genes, suggesting a role for APE1, XRCC1, PARP1 and OGG1 in colorectal carcinogenesis." (PMID 25268610, 2014). "The induction of oxidative DNA damage led us to ask if nontoxic doses of alkannin could sensitize colorectal cancer cells to inhibition of PARP1/2." (PMID 33519476, 2020).
hepatocellular carcinoma (62 papers, 2008 to 2025). A malignant tumor that arises from hepatocytes. "Further, the loss of PARP1 exacerbates lymphogenesis in DNA-PK-null mice and promotes hepatocellular carcinoma in Ku80 heterozygous mice." (PMID 30459355, 2019). "Interestingly, in hepatocellular carcinoma, high levels of both PARP1 and PARG are associated with an unfavorable prognosis." (PMID 38139034, 2023). "AP-2α directly regulates transcription of critical DNA repair genes such as TOP2A, NUDT1, POLD1, and PARP1 in hepatocellular carcinoma, thereby facilitating repair of oxidized DNA lesions." (PMID 41373739, 2025). "In different cancer cell lines, PARP-1 expression was increased in hepatocellular carcinoma, and in non-small-cell lung cancer cell lines, it was resistant to cisplatin." (PMID 38727308, 2024). "In hepatocellular carcinoma, copper with disulfiram inhibits T-cell infiltration by inhibiting PARP1 activity and enhancing GSK3β Ser9 site phosphorylation, which in turn upregulates PD-L1 expression." (PMID 37822927, 2023). "This study explores the function of TRIP13 and synergistic effects of TRIP13 and PARP1 inhibitors in hepatocellular carcinoma (HCC)." (PMID 35517402, 2022). "Peiminine also decreases poly (ADP-ribose) polymerase (PARP) activity in hepatoma cells, and increases the expression of Bax, caspase-3, caspase-8, caspase-9, and cleaved PARP1, ultimately leading to apoptosis." (PMID 36532788, 2022). "Zhou and colleagues further found DSF combined with copper (DSF/Cu2+) was reported to upregulate PD-L1 expression by suppressing PARP1/GSK3β in hepatocellular carcinoma cells and ultimately prevented CD8+ TIL infiltration." (PMID 34858816, 2021). "Such a PARP-1 signaling pathway induced necrosis was also found in human hepatocellular carcinoma SK-Hep1 cells and HT-22 cells." (PMID 25887795, 2015). "Inhibition of PARP-1 significantly suppressed human hepatoma cell proliferation and induced G0/G1 cell cycle arrest due to Sp1 transactivation." (PMID 24367566, 2013). "Results showed that forced expression of wild-type PARP-1 dramatically promoted the proliferation of human hepatoma cells in a time-dependent manner, while the mut-PARP-1 failed to affect it." (PMID 24367566, 2013). "In summary, our work demonstrated that PARP-1 inhibition blocked the growth of the human hepatoma cell line." (PMID 24367566, 2013). "HOXB7 and RARA are schizophrenic genes with different gene expressions, modulated through the retinoid signaling pathway by the hepatocellular carcinoma over-expression gene PARP1." (PMID 24564241, 2013). "In this study, we presented the first evidence that inhibition of PARP-1 induced cell cycle arrest at the G1-S checkpoint in hepatoma cells." (PMID 24367566, 2013). "Hepatocellular carcinoma (HCC) cells critically depend on PARP1 and CHK1 activation for survival." (PMID 39859548, 2025). "Furthermore, combining DCZ0415 and olaparib (a poly [ADP-ribose] polymerase [PARP1] inhibitor) has synergistic anticancer effects against hepatocellular carcinoma cells." (PMID 37627217, 2023). "Furthermore, another study has shown that DSF-Cu combination can impede GSK3β activity via the inhibition of PARP1, resulting in immunosuppression via PD-L1 stabilization in hepatocellular carcinoma." (PMID 37259318, 2023). "To test whether treatment with MBP-11901 induces the apoptosis of hepatocellular carcinoma cells, we evaluated the levels of protein expression of apoptosis markers in HepG2 cells, such as cleaved PARP1 and active caspase-3." (PMID 35454900, 2022). "Furthermore, a heterodimer of EGFR and MET can phosphorylate Y907 of PARP1 in the nucleus of hepatocellular carcinoma and contribute to this resistance." (PMID 32093123, 2020). "In this study, we also showed that Sp1 was poly(ADP-ribosyl)ated by PARP-1 in hepatoma cells." (PMID 24367566, 2013). "We then speculated that the regulatory functions of PARP-1 in the proliferation of hepatoma cells might base on the enzymatic activity of PARP-1." (PMID 24367566, 2013).